TNF (tumor necrosis factor)
Diseases named in the same sentence as TNF in open-access papers (continued):
Sharing a sentence is not in itself a finding about the gene and the disease.
inflammation (continued). "By contrast, in chronic inflammation, TNF-α-sTNFR1 complexes improve the function of TNF-a by slowing its release." (PMID 36038915, 2022). "As a second assessment of pulmonary inflammation, levels of the inflammatory mediators CRP, KC, TNF-α, and VEGF-A were measured in BALF." (PMID 36466426, 2022). "Significant changes in inflammatory and endothelium-specific variables IL-1β, IL-6, TNFα, oxLDL, H2O2, NO, 3-nitrotyrosine, and endothelial progenitor cells (OR 7.61, 95% CI 2.56–29.05, p < 0.0001), confirmed their interplay in vascular inflammation." (PMID 36362055, 2022). "We already confirmed that intraperitoneal injection of TNF-α induced vascular inflammation, such as macrophage infiltration and abnormal mRNA expression of VCAM-1 and inflammatory cytokines such as IL-6 and TNF-α in the mouse aorta." (PMID 34679642, 2021). "Previous research has shown that IL-6, IL-1β, MCP-1, NF-κB, TNF-α, ICAM-1 and VCAM-1 are all involved in the process of vascular inflammation." (PMID 34830730, 2021). "Clearly, GMP showed capacity in fighting OxS in the circulation (MDA and F2 isoprostanes) and liver (GPx1), and in alleviating liver inflammation, which is documented by a decline in inflammatory biomarkers (COX-2, TNF-α and IL-6)." (PMID 34572325, 2021). "Improve lung inflammation by inhibiting the excessive recruitment of M1 and M2 under TGF-β1 to achieve a therapeutic effect, reducing the levels of MCP-1, TNF-α, IL-1β, IL-6, IL-10,IL-13, and OSM." (PMID 34489700, 2021). "In IEC-6 cells IS treatment induced a significant increase in TNF-α release, COX-2 and iNOS expression as well as in nitrotyrosine formation, thus indicating IECs as a target of IS-induced intestinal inflammation." (PMID 33498967, 2021). "The increased production of proinflammatory cytokines and chemokines, including TNF-α, IL-6, IL-8 and MCP-1, during H. pylori gastric mucosal inflammation, has been well documented." (PMID 32230910, 2020). "After the model of intestinal inflammation was induced, the addition of FDC reduced the secretion of IL-10, IL-4, and TNF-α, indicating that FDC can slightly relieve intestinal inflammation." (PMID 32765533, 2020). "The results of Elisa (IL-6, MCP-1, TNF-α, and IL-1β) in the BALF and HE in the lungs of mice showed that Tre alleviated CS-induced pulmonary inflammation." (PMID 31947943, 2020). "The challenge of LPS to alveolar cells induced lung inflammation entailing the secretion of MCP-1 and TNF-α through activating NF-κB-responsive mechanism(s)." (PMID 31480536, 2019). "The GPR55 inhibitor CID16020046 reduced TNF-α, IL-1β, IL-6, and COX-2 levels in a mouse model of intestinal inflammation." (PMID 30453998, 2018). "As a result of cardiac inflammation, the IL6, TNFα and MCP1 transcription levels were also higher in post-infarcted myocardium, and this effect was inhibited by Mst1 knockout." (PMID 29760744, 2018). "To demonstrate the effect of curcumin on mice BAL fluids, we detected the secretion of the pro‐inflammatory cytokines TNF‐α, IFN‐α, and IL‐6, which contribute to IAV‐induced lung inflammation." (PMID 28646616, 2017). "Our findings about the TNF-induced dynamics in mRNA stabilome in RA FLS suggest that targeting of pathways that stabilize TNF-induced mRNAs can be used to modulate FLS activation and production of arthritogenic mediators in settings of synovial inflammation." (PMID 28708839, 2017). "In our cellular model of endothelial inflammation, i.e. HMEC-1 cells exposed to TNF-α, we observed formation of lipid droplets containing lipids of unsaturated characteristics." (PMID 28098251, 2017). "Inhibition of ICAM-1 by AIA significantly decreased the bladder inflammation grade and mast cell counts, which was accompanied by a reduction of purinergic receptors (P2X2/P2X3), prostaglandin E2, EP1/EP2 receptors, TNF-α, NK1R, and ICAM-1." (PMID 27782122, 2016).
inflammation (continued). "In vivo, the functional relevance of ERG's anti-inflammatory role was demonstrated using a murine model of TNF-α-dependent acute inflammation, where over-expression of ERG in the mouse paw decreased TNF-α-induced paw swelling." (PMID 27208692, 2016). "In vitro, co-culture of differentiated 3T3-L1 adipocytes and RAW264 macrophages is used as the model of adipose inflammation in which pro-inflammatory cytokine genes and proteins such as CCL2, IL-6 and TNF-α are significantly upregulated." (PMID 26901838, 2016). "LPS challenge promotes NF-κB nuclear translocation and binding to the TNF-α promoter, followed by TNF-α mRNA expression and pulmonary inflammation." (PMID 26990441, 2016). "On the other hand, chronic inflammation is known to be enhanced with healthy aging, and we found that inflammatory factors such as CRP, adiponectin, TNF-α, and IL-6 were elevated in SSCs." (PMID 26559536, 2015). "Taken together, our data demonstrate that VASP, which is negatively regulated by TNF-α, induces HIF-1α activation during the acute pulmonary inflammation process and plays an important role in the impairment of the alveolar-capillary barrier." (PMID 25051011, 2014). "Inflammatory factors such as ICAM-1, VCAM-1, TNFα, IL-6, and CRP have key roles in mediating vascular inflammation and blocking RAAS negatively modulates the levels of these inflammatory molecules." (PMID 24804145, 2014). "To explore the mechanisms through which andrographolide inhibits TNF-α-induced vascular inflammation, we examined the effects of andrographolide on the status of p38MAPK, ERK1/2, and JNK activation in TNF-α-stimulated VSMCs." (PMID 25114952, 2014). "Taken together, our data demonstrate that HIF-1α acts downstream of TNF-α to inhibit VASP expression and to modulate the acute pulmonary inflammation process, and these molecules play an important role in the impairment of the alveolar-capillary barrier." (PMID 25051011, 2014). "In a model of organic dust-induced airway inflammation, TLR2 knockout mice had significantly lower airway neutrophils, IL-6, TNF-α, and CXCL-1 (mouse homolog of CXCL8) compared with wild-type controls suggesting that airway inflammation is dependent on TLR2." (PMID 23606791, 2013). "It was reported that early application, 2 hours before LPS stimulation, of dexamethasone can reduce pulmonary inflammation and fibrosis after LPS-induced ALI in rats via the inhibition of TNFα mRNA expression." (PMID 23997804, 2013). "Component consisted of measurements corresponding to neutrophilic airway inflammation (sputum neutrophil cell count and sputum supernatant IL8) and systemic inflammation (plasma TNF-α) explaining the most variability in the data (20.2%)." (PMID 19480658, 2009). "Besides neurogenic inflammation, virus-induced airway inflammation and the accompanying release of cytokines, such as IFN-γ, TNF-α, or IL-1β, are known to demonstrate an impact on airway hypersensitivity and, therefore, an increase in coughing." (PMID 40722746, 2025). "LPS can cross the intestinal barrier into the body circulation and reach the lungs, where it exacerbates COPD lung inflammation through the toll-like receptor 4/ nuclear transcription factor-κB (TLR4/ NF-κB) signaling pathway mediating the production of IL-1β, IL-6, IL-17 TNF-α." (PMID 40098933, 2025). "Analysis demonstrated that median TNFα level was significantly higher in absence of AAAs, and in patients whose ocular inflammation was quiescent." (PMID 41459518, 2025). "The analysis of mRNA expression revealed that TNF-α, IL-1β, and IL-6 levels were higher in the colons of the HFV group, when compared with those of the NDV group, indicating high-fat/calorie diet-induced gut inflammation." (PMID 40284250, 2025). "Combined with the correlation analysis that PIEZO1 expression was positively correlated with inflammatory mediators, IL-1β, TNF-α, and IL-6, it is speculated that PIEZO1 might play a vital role in the development of pulpal inflammation." (PMID 38627713, 2024).
inflammation (continued). "In both a mouse model of HBV-induced liver inflammation and patients with advanced viral-related chronic liver disease, the intrahepatic CD14+HLA-DRhighCD206+ myeloid population is proinflammatory and spontaneously produces high levels of TNF-α." (PMID 38413535, 2024). "Moreover, IL-1β and TNF-α have been indicated to play a prominent role in the development of AHR and neutrophilic airway inflammation." (PMID 36803977, 2023). "Overall, these DEPs are involved in tissue remodeling in the setting of active chronic inflammation in OBM patients interacting to upregulate RANKL and TNF alpha signaling and targeting NF-κB, MAP Kinase and PPAR induced macrophage and neutrophil dependent tissue remodeling." (PMID 38092892, 2023). "In vitro decrease of the level of β-glucuronidase and lactate dehydrogenase in MSU-treated PMNL cells in a concentration-dependent manner.Significant in vivo reduction of the increased lysosomal activity, lipid peroxidation, TNF-α levels and paw volume in the MSU-induced inflammation mouse model." (PMID 38256888, 2023). "Moreover, elevated TNF-α is also reported to stimulate the release of MCP-1, thereby playing a major role in renal inflammation and fibrosis." (PMID 38201260, 2023). "Besides, both have been successfully implemented in the study of lung inflammation, showing cytokine responses upon proinflammatory triggers such as lipopolysaccharide (LPS), interferon gamma (IFN-γ) or tumor necrosis factor alpha (TNF-α)." (PMID 35832493, 2022). "The elevated levels of proinflammatory cytokines, such as IL-1β, TNF-α, and COX-2, could aggravate the progression of RA and could contribute to synovial inflammation and cartilage damage." (PMID 35401173, 2022). "The anti-inflammatory abilities of CS extract were also determined in HFD mice and we found a significant increase in IL-6 and TNF-α levels of serum and liver in the HFD group in comparison to the control group indicating an occurrence of systemic chronic inflammation (p < 0.05)." (PMID 35978956, 2022). "Therefore, autophagy inhibition can reduce LPS-induced lung inflammation and the severity of ALI by reducing the lung weight factor in bronchoalveolar fluid (BALF) and TNF-α, or increasing PaO2 content." (PMID 36310624, 2022). "Activated IL-17 also activates epithelial cells, fibroblasts, and macrophages, releasing granulocyte-macrophage colony-stimulating factor (GM-CSF), TNF-α, PGE2, IL-1, IL-6, and IL-8, which are not only involved in airway remodeling but also promote further exacerbation of airway inflammation." (PMID 35815290, 2022). "In the current study, we show for the first time that TLR9−/− mice exhibit a low bone mass and low-grade systemic chronic inflammation, which is characterized by the expansion of CD4+ T cells and increased levels of inflammatory cytokines, including TNFα, RANKL, and IL1β." (PMID 35624094, 2022). "Previously, we showed that monocytes were exclusively recruited to the brain vasculature in mice with liver inflammation, not neutrophils, and this recruitment led to increased levels of tumor necrosis factor (TNF) and CCL2 within the CNS." (PMID 35379260, 2022). "In other studies, LPS (lipopolysaccharide)-induced lung inflammation was relieved by the treatment with both whole clove aqueous extract and eugenol through a reduction of TNF-α (tumor necrosis factor alpha) and inhibition of NF-κB signaling, also with improvement in the alveolar damage." (PMID 33810416, 2021). "Although these antibodies did not decrease serum levels of proinflammatory cytokine TNF-α, they reduced lung inflammation and kidney injury in mice with 12 h I/R." (PMID 34381442, 2021). "This is consistent with observations in patients suffering from chronic intestinal inflammation who have exacerbated levels of TNF family cytokines in the intestinal tissue, and in mice where constitutive TNFα production leads to “Crohn’s like” inflammation in the small intestine." (PMID 34948118, 2021).
inflammation (continued). "Chronic inflammation is a major factor affecting the ovarian microenvironment in patients with PCOS inducing higher ovarian androgen production, which involves two pro-inflammatory cytokines, interleukin-1 beta (IL-1β), and tumor necrosis factor (TNF-α)." (PMID 34233746, 2021). "These immune cells present in adipose tissue can produce pro-inflammatory cytokines (e.g., interleukin (IL)-1b, IL-6, tumor necrosis factor –TNF-) as well as less anti-inflammatory cytokines (e.g., adiponectin and IL-10), which sustain the state of low-grade chronic inflammation." (PMID 34836334, 2021). "The concentrations of IL-4, 6, TNF-α, and eotaxin in the bronchoalveolar lavage fluid (BALF) decreased over time, and the levels of these inflammation indicators are consistent with the following inflammatory cell data and acute lung inflammation by ZnO NP." (PMID 34941770, 2021). "Accordingly, Exo-d-MAPPS significantly improved respiratory function, downregulated serum levels of inflammatory cytokines (TNF-α, IL-1β, IL-12, and IFN-γ), increased serum concentration of immunosuppressive IL-10, and attenuated chronic airway inflammation in CS-exposed mice." (PMID 32257769, 2020). "Accumulating evidence has uncovered that CD4+ T cells are critical for the development and progression of chronic intestinal inflammation, and CD4+ T cell-related cytokines (such as TNF-α, IFN-γ, IL-1β, and IL-17) are upregulated in the inflamed mucosa of patients with IBD." (PMID 32547537, 2020). "The results suggest that TNF-α-induced adipose inflammation is mainly mediated via the JNK/c-Jun pathway rather than NF-κB signaling." (PMID 32752112, 2020). "We have provided evidence that TNFα, an inflammatory cytokine that is central for the perpetuation of non-type 2 airway inflammation in stable COPD, induces the activity of p38MAPKγ in HASMCs." (PMID 31766770, 2019). "Our data show that TNF targeting DRG represents a mechanism independent of spinal sensitization which elicits articular hypernociception after resolution of acute joint inflammation." (PMID 32038637, 2019). "Two optimized lead NBD mimetics, SR12343 and SR12460, inhibited tumor necrosis factor α (TNF-α)- and lipopolysaccharide (LPS)-induced NF-κB activation by blocking the interaction between IKKβ and NEMO and suppressed LPS-induced acute pulmonary inflammation in mice." (PMID 29889904, 2018). "Interestingly, even if TNFR1 KO mice displayed amounts of IFN-γ 13-fold higher than WT, this was significantly lower than TNF KO and TNFR1R2 KO mice, indicating a role for both TNFR1 and TNFR2 in BCG induce pleural inflammation." (PMID 29973541, 2018). "Therefore, we studied local mRNA levels of additional cytokines that have been associated with ILC3 homeostasis, such as CXCL6, IL-1β, IL-12, IL-18, and IL-23 and/ or intestinal inflammation, including IL-1β, TGF-β, IFN-γ, and TNF-α." (PMID 28505204, 2017). "Our results clearly show that AHR was significantly suppressed in NEt-4IB-treated mice in a dose-dependent manner, with attenuation of not only eosinophilic airway inflammation and Th2 cytokine production in the BAL fluid and goblet cell metaplasia in the lung but also TNF-α levels in the lung." (PMID 28114934, 2017). "The ELA group exhibited increases in alveolar neutrophil infiltration, the numbers of TNF-α, MAC-2, MMP-9, MMP-12, TIMP-1, eNOS, and iNOS-positive cells and the volume fraction of the 8-iso-PGF2 α, suggesting the presence of lung inflammation, remodeling, and oxidative stress processes." (PMID 27528793, 2016). "In order to investigate whether feeding a HFD for 16 weeks induces cardiac inflammation, protein expression of major pro-inflammatory cytokines was quantified as direct or indirect measure of TLR4 signaling (i.e., IL-6/TNF-α and SOCS-3, respectively)." (PMID 26539824, 2015).
inflammation (continued). "Interestingly, during joint inflammation, overexpression of CLEC5A/MDL-1 recruits inflammatory cells and induces the production of IL-1, IL-6, IL-17A, and TNF, contributing to cartilage damage and bone erosion." (PMID 26086874, 2015). "Tumor necrosis factor alpha (TNF-α) is a pro-inflammatory key molecule promoting the perpetuation of chronic intestinal inflammation in IBD, and anti TNF-α therapies are potent treatment options within current IBD-therapies for a substantial portion of IBD patients." (PMID 25963636, 2015). "We measured subjects' clinical symptoms and signs and the levels of IL-8, TNF-α, IL-17, and IL-23 in the blood and sputum before and after treatment and thereby investigated the effects of LHQW on airway inflammation of AECOPD and its possible mechanism of action." (PMID 24971150, 2014). "SIRS was assessed by serum proinflammatory cytokines (TNF-α, IL-1β, CXCL1, IL-6), ALI was assessed by lung inflammation (lung myeloperoxidase [MPO] activity), and AKI was assessed by serum creatinine, BUN, and glomerular filtration rate (GFR) (by FITC-labeled inulin clearance) at 4 hours." (PMID 24265742, 2013). "TNF has been demonstrated to play a key role in human IBD and in experimental models of autoimmune colitis in mice, where TNF induces intestinal epithelial cell apoptosis during intestinal inflammation, thereby aggravating the disease." (PMID 24023849, 2013). "Taken together, the results above suggest that ADAM17 is the primary sheddase of L-selectin and TNF-α by alveolar leukocytes, but not of the IL-6R during acute pulmonary inflammation." (PMID 21603616, 2011). "Using TLR2- and TLR4-deficient mice, we further demonstrated that PM2.5-induced increases in BAL cell counts, ROS, IL-6, and TNF-α were partially attenuated in TLR4 knockout mice, indicating a contributory but not exclusive role for TLR4 signaling in PM2.5-driven pulmonary inflammation." (PMID 41596147, 2026). "Chronic inflammation, defined as a prolonged, low-grade inflammatory response that persists over time, is characterized by elevated levels of circulating pro-inflammatory markers such as C-reactive protein (CRP), interleukin-6 (IL-6), and tumor necrosis factor-alpha (TNF-α)." (PMID 39519418, 2024). "Data obtained indicate that finasteride withdrawal induces gut inflammation in adult male rats and that ALLO treatment is able to counteract some of these alterations, such as the increase in the levels of pro-inflammatory cytokines (i.e., IL-1β and TNF-α) and serotonin." (PMID 36358917, 2022). "Inflammation mediators such as NO, PGE2, interleukin 6 (IL-6), tumor necrosis factor-alpha (TNF-α), and interleukin 8 (IL-8) are some examples of cell signaling molecules that promote prolonged inflammation, and if uncontrolled can result in chronic inflammation." (PMID 35056836, 2022). "Furthermore, adipose IL-6 and TNF-α mRNA levels were significantly higher in SERT−/− adipose compared with WT, indicating that lipid accumulation in SERT−/− mice stimulated adipose inflammation." (PMID 28442777, 2017). "While the negative effects of TNF on bone formation are well documented, synovial inflammation in fact appears to also provoke an osteoblastic response, which may be seen as an attempt at bone repair." (PMID 16507121, 2006). "For example, pro‐inflammatory mediators including IL‐1β, IL‐6, and TNF‐α promote a reduction in the NAD+/NADH ratio, leading to an impairment in mitochondrial biogenesis, while mitochondrial dysfunction may induce cardiac inflammation via the release of mitochondrial DNA or formation of ROS." (PMID 37365150, 2023). "In addition to pulmonary inflammation, there is also systemic inflammation with increased levels of fibrinogen, C-reactive protein (CRP), serum amyloid A (SAA), and pro-inflammatory cytokines tumor necrosis factor-alpha (TNF-α), interleukin-6 (IL-6), and IL-8 in the serum." (PMID 34681202, 2021).